PPARA (peroxisome proliferator activated receptor alpha)
Diseases named in the same sentence as PPARA in open-access papers (continued):
Sharing a sentence is not in itself a finding about the gene and the disease.
breast cancer (continued). "Similarly, it has been shown that activation of PPARα enhances cell proliferation in rat mammary glands and the human breast cancer cell lines." (PMID 35740412, 2022). "Knockdown and overexpression experiments in hepatocytes and breast cancer cells demonstrated that cyclin D1 represses fatty acid oxidation by inhibiting peroxisome proliferator-activated receptor alpha (PPARα) activity, a nuclear receptor that induces fatty acid oxidation." (PMID 33494394, 2021). "PPARα was demonstrated to act as an oncogene, especially in breast cancer." (PMID 34199293, 2021). "Based on these findings, a potential miR-1908-3p-mRNA regulatory network, miR-1908-3P-ID4/ LTBP4/ GPM6B/ RGMA/ EFCAB1/ ALX4/ OSR1/ PPARA, contributing to breast cancer onset and progression could be established." (PMID 32650755, 2020). "In breast cancer cells, higher levels of PPARα are found when compared to HMEC cells." (PMID 30717356, 2019). "However, the role of PPARα in the regulation of CYP1B1 expression in breast cancer cells has been unclear." (PMID 31775380, 2019). "It has been shown that PPARa is active in breast cancer and its inhibition leads to cell death." (PMID 31141879, 2019). "Moreover, PPARα activation enhances breast cancer cell proliferation by upregulating cyclin E levels." (PMID 31791289, 2019). "Although limited research has investigated the possible link between PPARα and breast cancer, the biology of the gene suggests that it could play a role in the pathology." (PMID 29502166, 2018). "We examined the YMR score of the FOXM1 and PPARα pathways in breast cancer cell lines." (PMID 29301506, 2018). "Our current findings provide a mechanistic explanation of how PPARα agonists could act as effective anti-inflammatory and anti-proliferative agents for breast cancer cells." (PMID 26621841, 2016). "To test whether viability of other cancer cells is susceptible towards fibrates and overexpression of PPARα-tr, we performed the same experiments in the human ovarian carcinoma cell line, SKOV3 and the human breast cancer cell line, MCF7." (PMID 26122096, 2015). "While tumor suppression by PPARα has been reported in some cancers including melanoma and glioblastoma, PPARα has also been found to lead to progression of tumor growth in other cancers including hepatocellular carcinoma and breast cancer." (PMID 23951092, 2013). "Most have been implicated in tumor biology, and many of these gene sets have been implicated in breast cancer progression, including chromosomal region 1p33, matrix metalloproteinases (including MMP12), and sequence targets of peroxisome proliferator-activated receptor alpha." (PMID 21627793, 2011). "Furthermore, agonism of PPARα has been shown to increase proliferation in MCF-7 breast cancer cells." (PMID 16569247, 2006). "A parallel might be drawn between the effect of fenofibrate (a PPARα agonist) in endometrial cancer and thiazolidenediones (TZDs, PPARγ agonists), such as rosiglatazone and troglitazone, in breast cancer." (PMID 16569247, 2006). "Consequently, further investigation is required to elucidate the role of PPARα in breast cancer." (PMID 40002245, 2025). "Therefore, it also might be intimated that PPARα agonists, including fenofibrate as an activator of fatty acid oxidation, might have an effect as a target drug for ER+ breast cancer, although this needs to be justified through further study." (PMID 35008972, 2022). "Similarly, breast cancer cells produced metabolites of the 5-lipoxygenase pathway to activate the peroxisome proliferator-activated receptor α (PPARα) in B cells, resulting in tBreg generation; unsurprisingly, inactivation of PPARα prevented tBreg-mediated cancer escape." (PMID 33193391, 2020).
breast cancer (continued). "Although fenofibrate promotes breast cancer cell apoptosis via NFκB-mediated activation of caspase-3 and expression of Bad, which is independent of PPARα activity, clofibrate or wyeth induces hepatocarcinoma HepG2 cell apoptosis and inhibits tumor progression in a PPARα-dependent manner." (PMID 28948004, 2017). "Lack of PPARα expressions are associated with shorter breast cancer-specific survival." (PMID 28948004, 2017). "The fact that PPARα agonists are reported to inhibit tumor growth in various cancer model systems led us to examine how activation of PPARα might affect the growth of breast cancer cells." (PMID 26621841, 2016). "We conducted an examination of the CCR2/PPARα/ATGL pathway in adipose tissues adjacent to normal breast tissue (non‐peritumoral AT) and those adjacent to breast cancer tissue (peritumoral AT) from the same patients." (PMID 41160815, 2026). "A substantial body of evidence has demonstrated that the PPARα agonist clofibrate enhances the biological activities of ACSL1 and CPT1 enzymes, thereby facilitating FAO in breast cancer cells." (PMID 40002245, 2025). "The NuRD (MTA1) complex promotes EMT through transcriptional repression of peroxisome proliferator-activated receptor α (PPARα) and superoxide dismutase 2 (SOD2) in breast cancer." (PMID 39154024, 2024). "Thus, RUNX2 and PPARα may be potential therapeutic targets for breast cancer bone metastasis." (PMID 35534547, 2022). "Zang and colleagues reported that the dual PPARα/γ agonist TZD18 provoked apoptosis in human leukemia, glioblastoma, and breast cancer cell lines through the induction of the endoplasmic reticulum stress response." (PMID 35954274, 2022). "Also, on experimental basis, nuclear receptor agonists, like PPARα/γ agonists combined with all-trans retinoic acid unfold activity by modeling stroma and tumor cells, thereby reducing aromatase activity in neighboring fat cells in the breast and negatively impact breast cancer stem cell survival." (PMID 35814409, 2022). "Ten breast cancer samples were collected and performed tissue microarray analysis via immunohistochemical staining to examine the expression of RUNX2 and PPARα." (PMID 35534547, 2022). "In summary, our results showed that RUNX2 expression was upregulated in multiple carcinomas including breast cancer, while PPARα was downregulated in breast cancer, suggesting the potential of RUNX2 as a biomarker of breast cancer." (PMID 35534547, 2022). "Consistent with our observation that PPARα was a downstream target of RUNX2, the expression of PPARα was found to be downregulated in these breast cancer samples and the level of its expression is negatively correlated with RUNX2." (PMID 35534547, 2022). "PPARα and SOD2, which inhibited breast cancer bone metastasis, were found to be the target genes of the RUNX2/NuRD(MTA1)/CRL4B complex." (PMID 35534547, 2022). "Elevated CD47 expression is reported in HER2 positive breast cancer HCC1954 and MCF7 cells and NF-κB and PPARα are detected in the super-enhancer of CD4752." (PMID 32929084, 2020). "The potential target genes of miR-1908-3p in breast cancer included ID4, LTBP4, GPM6B, RGMA, EFCAB1, ALX4, OSR1 and PPARA." (PMID 32650755, 2020). "In liver and breast cancer cells, knockdown of CCND1 gene leads to increased PPARα transcriptional activity, expression of PPARα target genes, and fatty acid oxidation." (PMID 33317149, 2020). "In this study, we investigated the effects of WY-14643, a peroxisome proliferator-activated receptor α (PPARα) agonist, on CYP1B1 expression and the related mechanism in MCF7 breast cancer cells." (PMID 31775380, 2019). "In this study, we investigated the effect of the PPARα agonist, WY-14643, on CYP1B1 expression and the related mechanism in breast cancer cells." (PMID 31775380, 2019). "PPARA and PPARG are also involved in the regulation of cholesterol metabolism, which was shown to regulate cell adhesion in breast cancer cell lines." (PMID 30974831, 2019).
breast cancer (continued). "Among them, cyclin D1, contrary to what has just been mentioned, was demonstrated to inactivate the PPARα-mediated gene expression of enzymes related to FAO in hepatocytes as well as hepatocellular and breast cancer-derived cell lines." (PMID 29966227, 2018). "Here, we detected high expression of PPARα in human primary inflammatory (SUM149PT) and highly invasive (SUM1315MO2) breast cancer cells, and tissue sections of human breast cancer." (PMID 26621841, 2016). "Compared to HMEC cells, increased expression of PPARα was observed in SUM149PT (3.9-fold) and SUM1315MO2 (3.7-fold) breast cancer cells." (PMID 26621841, 2016). "We have shown that the PPARα agonist clofibrate diminishes the level and activation of key survival kinases such as Nf-KB and ERK1/2 in breast cancer cell lines." (PMID 26621841, 2016). "It will be of considerable interest to evaluate the contribution of PPARα on changes in CPT1A expression and activity in breast cancer cells in response to PRL in future studies." (PMID 21294903, 2011). "Some authors have demonstrated that leptin increase cell proliferation which is an essential element for tumor metastasis, through cell progression in MCF-7 human breast cancer cells with up-regulation of PKC-α, PPARγ and PPARα." (PMID 16504019, 2006). "Using the PPARE-Luciferase reporter, we confirmed that the PPARα pathway is active in our breast cancer cells, KAIMRC1 cells, without adding any exogenous ligand." (PMID 39859448, 2025). "In the present study, we discovered two novel compounds, PHA665752 and NSC3852, which can modulate the PPARα pathway independently rather than binding directly to the receptor itself, and we highlighted their impact on breast cancer cells." (PMID 39859448, 2025). "Briefly, the ER + breast cancer cell lines, T47D and ZR75, were co-transfected with the NNAT promoter-reporter construct, and plasmids that constitutively expressed E2F1, E2F4, NRF1, PPARα/RXR, PPARγ/RXR, or control (pLX304)." (PMID 37400769, 2023). "Furthermore, the expression of PPARα and SOD2 was explored in normal and breast cancer tissues from published datasets (GSE42568, GSE14548, and GSE54002)." (PMID 35534547, 2022). "As expected, both PPARα and SOD2 were significantly downregulated in breast cancer." (PMID 35534547, 2022). "Functional experiments demonstrated that RUNX2/NuRD(MTA1)/CRL4B complex could promote EMT and bone metastasis by inhibiting the expression of PPARα and SOD2 in breast cancer." (PMID 35534547, 2022). "Consequently, the pharmacological inhibition of PPARα reduced ANGPTL4 expression, which is involved in adipose-tissue-induced β-oxidation, proliferation, and the invasion of breast cancer cells." (PMID 35954274, 2022). "In order to investigate the possible relationships between CPT1 genes and PPARα, were performed some analyses on two different cancer cell lines, MDA-MB-231 (breast cancer cell line) and PANC-1 (pancreas cancer cell line) with knockdown or overexpression of the PPARα gene." (PMID 29966227, 2018). "As PRL mediates its effects via, among others, JAK2/STAT5 signaling in breast cancer cells, this could provide a means by which PRL could directly activate PPARα transcription independent from LKB1 and AMPK." (PMID 21294903, 2011). "PPARA, PPARD, and PPARG were involved in many of the indirect effects identified in breast cancer." (PMID 18358079, 2008). "Notably, it has been shown that breast cancer patients that lacked PPARα expression had a significantly shorter overall survival." (PMID 37237519, 2023).
breast cancer (continued). "Additionally in endometrial cancer, breast cancer, glioblastoma, colon cancer, ovarian cancer, medulloblastoma, neuroblastoma, pancreatic cancer, and NSCLC, the activation of PPARα induced apoptosis." (PMID 35954274, 2022). "Besides these in vivo data, AA was found to stimulate the growth rate of three breast cancer cell lines (one triple negative and two triple positive) in correlation with PPARα expression and activity." (PMID 22811918, 2012). "The published breast cancer dataset (GSE48390) revealed a positive correlation between RUNX2, MTA1 and CUL4B, and negative correlations among RUNX2/MTA1/CUL4B and PPARα/SOD2." (PMID 35534547, 2022). "In breast cancer, FASN–PPARα functions as a negative feedback loop axis where PPARα activation is shown to suppress FASN expression through SREBP-1c inhibition." (PMID 32872164, 2020).
hepatocellular carcinoma (165 papers, 2007 to 2026). A malignant tumor that arises from hepatocytes. "Nevertheless, it is well known that PPARα weakly expresses and has very low function in HepG2 cells, because the cells are originated from hepatoma and some kinds of genes, such as PPARα, is mutated." (PMID 23680128, 2013). "PPARA is a member of the Peroxisome proliferator-activated receptors, and has been implicated in hepatocellular carcinoma development in rodents." (PMID 20052266, 2010). "In the Ppara-null and PPARA-humanized mice, there is an accumulation of hepatocellular lipids, leading to macrosteatosis (a form of hepatocellular toxicity) with consequent increased cellular proliferation and an increased risk of hepatocellular cancer." (PMID 37623879, 2023). "Prolonged activation of PPARα also increases signaling of hepatocyte proliferation and causes hepatocellular carcinoma in rodents, but PPARα-induced hepatocellular carcinoma appears to occur only in rodents, and there are species differences between rodents and humans in this aspect." (PMID 35622678, 2022). "Interestingly, a PPARα-dependent pathway DDR has been linked to events surrounding hepatocellular carcinoma, but its roles in liver fibrosis remain to be explored." (PMID 33261190, 2020). "A later study suggested a higher susceptibility of PPARα-knockout mice to diethylnitrosamine (DEN)-induced hepatocellular carcinoma (HCC)." (PMID 35954274, 2022). "Furthermore, in humans, sustained exposure to fibrates may increase the risk of hepatocellular carcinoma through a PPARα-dependent or -independent pathway." (PMID 28401920, 2017). "This microRNA also manifests antiproliferative properties against hepatocellular carcinoma cells, concomitantly reducing cellular steatosis and fibrosis by targeting PPARα and TIMP2." (PMID 41523988, 2026). "Quantitative PCR confirmed the induction of SLC25A47 mRNA by PPARα activation in human hepatocytes, human liver slices, and human hepatoma HepG2 cells." (PMID 39746607, 2025). "The direct molecular interactions between PAE and PPARA were also confirmed to exist in the occurrence of hepatocellular carcinoma in rodents." (PMID 41155171, 2025). "Supporting these findings, in vitro experiments demonstrated that HULC activates ACSL1 expression in HepG2 hepatoma cells via the miRNA-9/PPARA signaling pathway, thereby inducing lipid metabolic reprogramming that facilitates HCC progression." (PMID 40909946, 2025). "It has been well documented that PPARα activators suppress CYP7A1 gene promoter activity in human hepatoma HepG2 cells and that PPARα agonists, e.g., fenofibrate, downregulate cyp7a1 and cyp27a1 expression and reduce their activity in rodents." (PMID 39120326, 2024). "BCFAs have the potential to influence gene expression, for example, PPARα in rat hepatoma cells and IL-8 in human intestinal epithelial cells." (PMID 37850622, 2023). "In hepatocellular carcinoma, ectopic expression of PPARα in cancer cells significantly inhibits cell proliferation and induces apoptosis." (PMID 37251321, 2023). "The peroxisomal enzyme Acyl-CoA oxidase 2 (ACOX2) has been postulated as a tumor suppressor in hepatocellular carcinoma via the positive regulation of PPARα." (PMID 35954274, 2022). "The overexpression of peroxisome proliferator-activated receptor alpha (PPARα) increased the expression of miR-200c in hepatocellular carcinoma cells." (PMID 35682560, 2022). "Beta-catenin acts as an activator of PPARα, which stimulates fatty-acid oxidation as the major metabolic pathway of beta-catenin-dependent hepatocellular carcinoma." (PMID 35954274, 2022). "The PPARα activator fenofibrate has been shown to induce apoptosis in a human hepatocellular carcinoma cell line through an increase in reactive oxygen species (ROS)." (PMID 35954274, 2022). "For instance, lncRNA HULC is upregulated in hepatocellular carcinoma where it sequesters miR-9 and elevates peroxisome proliferator-activated receptor alpha (PPARA) levels." (PMID 36010595, 2022).